IL10 (interleukin 10)
Diseases named in the same sentence as IL10 in open-access papers (continued):
Sharing a sentence is not in itself a finding about the gene and the disease.
Sepsis (continued). "IL-10 concentrations can mirror the extent of the inflammatory status, with raised values being associated with adverse outcomes in sepsis." (PMID 36359365, 2022). "A previous study reported that IL‐10 was produced in response to insult, and the overproduction of IL‐10 was associated with severity and fatal outcome in patients with sepsis." (PMID 36444621, 2022). "The multifactorial logistic regression analysis forest plot revealed that PCT, IL-10, and IL-17 were independent risk factors for the development of sepsis (P < 0.05)." (PMID 35937269, 2022). "Our results also show a positive correlation between IL-10 and pro-inflammatory cytokines, whose simultaneous presence has been associated with the pathogenesis of sepsis." (PMID 36536294, 2022). "The production of IL-6, TNFα, IL-18, and IL-1 pro-inflammatory cytokines along with IL-10 (anti-inflammatory cytokine) is a hallmark response to sepsis." (PMID 36439175, 2022). "To further investigate the pro-inflammatory effect of exosomal delivery had on monocytes, we analysed the production of two major inflammatory cytokines frequently associated with sepsis mortality: IL-6 and IL-10." (PMID 36061862, 2022). "IL-10 in particular has been implicated as the primary endogenous modulator of inflammatory response during sepsis." (PMID 35563475, 2022). "An independent risk of sepsis development was shown to be associated with the presence of three markers: interleukin 10, interleukin 17, and procalcitonin (PCT)." (PMID 35937269, 2022). "Our results are similar to those of a recent publication that showed that miR-21 inhibition in myeloid cells in a sepsis model was associated with increased anti-inflammatory IL-10 in vivo and in vitro." (PMID 36139749, 2022). "Immunosuppression in sepsis is related to high levels of IL-10, which is directly linked to inflammation." (PMID 36036007, 2022). "Interleukin‐10 (IL10) is a well‐known anti‐inflammatory cytokine, which reduces inflammation and inhibits dysfunction of endothelial cells caused by sepsis." (PMID 35015384, 2022). "In adults with sepsis, high levels of IL-10 have been associated with a poor prognosis and have been shown to be a strong predictor of septic shock severity and fatality." (PMID 35449688, 2022). "In a prospective observational study including 106 burn patients, some of which developed sepsis, Treg frequency in peripheral blood was positively associated with the size of the burn area, as were IL-10 and TGF-β levels." (PMID 33021569, 2021). "Some studies have shown that indicators such as tumor necrosis factor-α (TNF-α), interleukin-6 (IL-6), and interleukin-10 (IL-10) are used as early biomarkers of sepsis-associated ARDS." (PMID 34095029, 2021). "Here we show that N-glycan from pathogenic C. albicans ameliorates mouse sepsis through immunosuppressive cytokine IL-10." (PMID 33727664, 2021). "This phenomenon increases susceptibility to opportunistic infections and sepsis (second hits), resulting in a higher secondary pro-inflammatory response and IL-10 rise after 72 hours." (PMID 35126355, 2021). "This trend follows through life, with males being more likely to die from sepsis than females, an observation associated with altered ratios of proinflammatory IL-6 and anti-inflammatory IL-10." (PMID 34489958, 2021). "Compared to control, sepsis was associated with higher levels of IL-6 (median 0.0 pg/ml vs. 703 pg/ml; ***p<0.001) and IL-10 (median 0.0 pg/ml vs. 217 pg/ml; **p<0.01) at the time of study inclusion." (PMID 33939725, 2021). "In a large multicenter observational study including 583 patients with severe sepsis, it was demonstrated that patients with high levels of IL‐6 and IL‐10 had markedly increased risk of dying (hazard ratio of 20.52)." (PMID 33719215, 2021). "In contrast, the Th type 2 (Th2) responses (secrete IL-4, IL-5, IL-13 and IL-10) were elevated, leading to a suppressed adaptive immune response and increased susceptibility to sepsis." (PMID 34209240, 2021).
Sepsis (continued). "A similar study investigated the association of IL-6 and IL-10 levels with mortality in patients with sepsis and septic shock." (PMID 34945111, 2021). "In sepsis and septic shock patients, upregulation of many cytokines, including IL-1β, IL-6, IL-8, IL-10, MCP-1, and G-CSF, was associated with increased mortality and positively correlated with patients’ SOFA scores." (PMID 32669536, 2020). "Currently, there is a consensus that imbalance between anti- and pro-inflammatory cytokines e.g. IL-6 and IL-10 is one of the cause of mortality in sepsis." (PMID 32015566, 2020). "Higher concentrations of IL-6 and IL-10 predict higher mortality rates in patients with sepsis; an elevated IL-6/IL-10 ratio is also associated with mortality in these patients." (PMID 33203111, 2020). "Earlier studies suggested that in critically ill patients with sepsis, lower levels of plasma IL-10 were associated with poor prognosis." (PMID 33123579, 2020). "The continued release of IL-10 contributes to sepsis-induced immunosuppression resulting in more susceptibility to nosocomial infection." (PMID 32772917, 2020). "High IL-10 levels serve as a marker of the immunosuppressive phase of sepsis associated with a poor patient prognosis." (PMID 32516170, 2020). "Our results are consistent with those from a recently published study conducted on sepsis patients which showed that although IL-6 and IL-10 were associated with mortality, the balance between these two cytokines did not impact mortality." (PMID 32015566, 2020). "IL-6 is associated with the occurrence of MODS and sepsis together with IL-10 within 24 h after trauma." (PMID 32492963, 2020). "Elevated IL-10 levels and a high IL-10/TNF-α ratio have been associated with mortality in severe sepsis patients, and similar findings have been previously reported among SAB patients." (PMID 33256638, 2020). "In trauma patients, increased IL-10 levels were associated with enhanced complication rates of sepsis, CARS and increased mortality." (PMID 32276346, 2020). "Increased levels of IL-10 in human patients with sepsis is associated with poorer outcomes and an increased risk of MODS and death." (PMID 30931316, 2019). "Albeit, systemic levels of IL-10 were significantly increased in patients with severe sepsis and linked to mortality as compared to patients with moderate sepsis." (PMID 31795299, 2019). "The 185 subgroup meta-analyses by ethnicity and age revealed three additive polymorphisms (TLR2 rs5743708 Arg753Gln, IL6 rs1800796-572G/C, and IL10 rs1800896-1082A/G) that were significantly associated with the risk of sepsis." (PMID 30683156, 2019). "Meanwhile, depletion of Treg cells in WT and Gpr174-deficient mice resulted in low levels of IL-10, which plays an important role in attenuating sepsis induced tissue damage." (PMID 30850582, 2019). "Nrp1 has been previously proposed as a cell marker for thymic-derived Treg cells; but its expression has also been described on T cells during allogeneic skin graft rejection, sepsis, IL-10 deficiency, and anti-tumor immune responses." (PMID 31068948, 2019). "First, the specific DNA methylation profiles of monocytes from patients with sepsis associate with IL-10 and IL-6 levels." (PMID 31665078, 2019). "Persistently elevated IL-10 levels in the plasma have also been correlated with a worse outcome in patients with sepsis and have been associated with the development of secondary complications after burn injury and trauma." (PMID 31014397, 2019). "Gpr174-deficient Treg cells controlled macrophage polarization via IL-10 dependent and cell-cell contact dependent pathway in LPS-induced sepsis." (PMID 30850582, 2019). "The development of sepsis in trauma patients was also linked to elevated systemic IL-10 levels on admission in an American study (n = 66)." (PMID 31795299, 2019).
Sepsis (continued). "For the IL10 rs1800871-819C/T variant, a significant association with the susceptibility to sepsis was only confirmed in the Asian population (OR = 1.35, 95% CI = 1.03–1.76, P = 0.03 for the recessive model)." (PMID 30683156, 2019). "Further support for the positive association between sepsis severity and immunosuppression are provided by reports of increased mortality in septic patients with elevated IL-10 levels or a high IL-10/TNFα ratio." (PMID 30555806, 2018). "While there is concomitant secretion of pro- and anti-inflammatory cytokines during sepsis, the increased ratio of IL-10 to TNFα is associated with sepsis mortality and immunosuppression, however, the mechanism for this association has yet to be elucidated." (PMID 30555806, 2018). "Interleukin 10 (IL-10) promoter polymorphism is associated with increased mortality in severe sepsis, susceptibility to chronic hepatitis C virus (HCV) infection, resistance to antiviral therapy, and predisposition to Epstein Barr virus (EBV) infection." (PMID 30245696, 2018). "Further work is needed to assess the causal link, if any, between inflammation, IL-10, HO-1 and neutrophil dysfunction in sepsis." (PMID 30046137, 2018). "Similar findings were obtained from a previous study in which remote ischemic conditioning induced a significant elevation in serum IL-10 levels in a murine sepsis model which was associated with reduced inflammatory responses and better survival." (PMID 29617450, 2018). "Our previous study revealed that among patients admitted to the ICU with sepsis, those with underlying active cancer had higher baseline levels of plasma IL-10, higher trend of G-CSF and higher mortality rate than those without active cancer." (PMID 29618837, 2018). "Severity of sepsis and risk of death is supported by a dysregulated host cytokine response with progressively increasing IL10/TNF ratio." (PMID 31058274, 2017). "Susceptibility to P. aeruginosa following CLP-induced sepsis has been linked to reduced IL-12 and increased IL-10 production by dendritic cells (DCs)." (PMID 28724977, 2017). "Among patients admitted to the ICU with sepsis, those with underling active cancer had higher baseline levels of plasma IL-10, higher trend of G-CSF and higher mortality rate than those without active cancer." (PMID 28692671, 2017). "In a rat model of sepsis-induced acute kidney injury, upregulating IL-10 expression by macrophages was associated with attenuation of sepsis." (PMID 29312312, 2017). "IL-10 is released by diverse leukocytes during sepsis and increases the susceptibility to secondary infections." (PMID 29218051, 2017). "For TLR4+896A/G variant allele carriers with severe sepsis, high plasma endotoxin/IL-10 inhibits HLA-DR expression and impaired phagocytosis were noted in their classical monocyte." (PMID 27861595, 2016). "In CAP patients, the IL6 rs1800795-C allele was associated with severe sepsis/septic shock/severe systemic inflammatory response, while the IL10 rs1800896-A allele protected against the development of these critical conditions." (PMID 27725770, 2016). "MSC-secreted prostaglandin-E2 leads increased macrophage IL-10 secretion and thus can attenuate sepsis and sepsis-associated lung injury." (PMID 26797607, 2016). "Subsequent clinical studies in sepsis have demonstrated the association of ET with high levels of circulating IL-10 and low levels of monocyte human leucocyte antigen - D related (HLA-DR) expression." (PMID 27252406, 2016). "Polymorphisms in IL10 are associated with sepsis mortality, and family studies of first-degree relatives and analysis of twins indicate that heritable genetic factors underlie inter-individual differences in quantitative IL10 production." (PMID 27128945, 2016). "An elevated plasma level of anti-inflammatory cytokines such as IL-10 is another hallmark of sepsis." (PMID 27574993, 2016).
Sepsis (continued). "IL-8 was shown to be a highly sensitive predictor for pediatric oncology patients at low risk for bacteremia while IL-10 was shown to correlate with bacteremia and sepsis." (PMID 26315105, 2015). "IL-10 reduced sepsis-associated hippocampal neuronal damage as a result of pneumococcal sepsis in mice overexpressing IL-10." (PMID 25563481, 2015). "Increased levels of both the proinflammatory chemokine IL-8 and the anti-inflammatory cytokine IL-10 have been associated with severe sepsis and poor outcome." (PMID 26612199, 2015). "In conclusion, we have found that the alternations in the genotype and allele frequency of IL-1β (−511C/T), TNF-α (−308 G/A), TNF-α (−238 G/A) and IL-10 (−1082 G/A) genes are associated with an higher risk of sepsis development in trauma patients and outcomes." (PMID 26561011, 2015). "The IL-1β, TNF-α and IL-10 polymorphism frequency was significantly higher in the post traumatic septic group than in the non-sepsis and appeared to be an independent risk factor for death due to septic shock." (PMID 26561011, 2015). "Polymorphisms at IL-10 promoters:-1082 (G/A), −819 (C/T) and −592 (C/A) are associated with resistance to sepsis in Caucasians population." (PMID 26561011, 2015). "IL-10 can reduce excessive inflammation in sepsis, and IL-10-deficiency leads to multiple organ failure and increased mortality rates in mice." (PMID 25780458, 2015). "Patients with allele T at IL-10 (−819) had 12.5 times more chances of developing sepsis as compared to non-sepsis (p = 0.001, OR (95 % CI) = 12.5, CI = 5.5-30.1)." (PMID 26561011, 2015). "Expressions masking of TNF-α was found to be linked with the degree of IL-10 presence in sepsis patients." (PMID 26561011, 2015). "An increase in the IL-6/IL-10 ratio, caused by a decrease in IL-10, has previously been associated to the severity of systemic inflammatory response syndrome in patients with sepsis." (PMID 25415590, 2014). "Elevated IL-10 levels have been associated with increased mortality after S. aureus bacteremia and among general populations with sepsis." (PMID 24505428, 2014). "Numerous studies have linked high circulating levels of IL-10 with poor outcome following burn injury, sepsis, and a wide variety of bacterial infections." (PMID 24454904, 2014). "High IL-10 levels are associated with bacteremia and sepsis in febrile pediatric cancer patients with neutropenia." (PMID 24839609, 2014). "In sepsis patients Trem-1 expression on neutrophils was associated with the IL-10 (LPS: r = 0,61, p < 0.02) and TNF-α inducibility (LPS: r = 0,78, p < 0,002)." (PMID 23414215, 2013). "Combined high levels of IL-10 and IL-6 are associated with a very high risk of death in sepsis patients." (PMID 23437050, 2013). "A quite unexpected finding of our study was the early increase of IL-10 and sCD25, which should be associated with the late/immunosuppressive stage of sepsis according to current literature." (PMID 23561467, 2013). "For example, the serum level of an anti-inflammatory cytokine IL-10 is shown to be associated with mortality in severe sepsis and recently in S. aureus bacteremia patients." (PMID 23565251, 2013). "The presence of kidney dysfunction prior to sepsis was associated with increased vascular permeability, bacteremia, elevated vascular endothelial growth factor and serum IL-10 levels and splenocyte apoptosis." (PMID 23548034, 2013). "IL-10 has been shown to repress sepsis-associated hippocampal neuronal damage as a result of pneumococcal sepsis in mice overexpressing IL-10." (PMID 23997430, 2013). "IL-10 levels are also significantly enhanced in co-infected mice like in sepsis where it is associated with a compensatory anti-inflammatory response." (PMID 23110184, 2012). "IL-10 has been implicated in BMSC therapy previously in sepsis and has been cited as one of the more influential factors upregulated during BMSC-mediated T-cell suppression." (PMID 23319959, 2012).
Sepsis (continued). "CARS results from the counter-regulating suppression of various cellular and humoral immune functions, and is characterized by an excessive production of anti-inflammatory mediators, such as interleukin-10 (IL-10), and is associated with the onset of sepsis." (PMID 22519539, 2012). "Key pro- and anti- inflammatory mediators like IL-1α, MIP-1β, RANTES, CXCL-1, IL-6 and IL-10, implicated to play a role in sepsis were up-regulated at both the early and late time points." (PMID 23009705, 2012). "Nonetheless, a significant association between sepsis and higher level of IL-10 determined by—1082 base pair single polymorphism in promoter region of IL-10 gene is equivocal." (PMID 22529517, 2012). "Interleukin-10 (IL-10) is considered to be a cytokine with potent anti-inflammatory properties, which have been previously linked to increased incidence of sepsis." (PMID 22529517, 2012). "Of specific interest, both IL-6 and IL-10 levels, which strongly correlate with survival outcome in sepsis, were significantly attenuated in SRA deficiency." (PMID 23071440, 2012). "Of interest, high concentration of plasma and cord blood IL-10 in preterm neonates evaluated for sepsis was associated with mortality and is considered as an early indicator of prognosis." (PMID 22114550, 2011). "An early imbalance of IL-10 in sepsis was shown to be associated with death despite TNFα production." (PMID 20076757, 2010). "At the time sepsis was first suspected in neonates, IL-10 had a sensitivity of 17% and a diagnostic specificity of 99%." (PMID 20490277, 2010). "In our study, IL-6 and 10, the NI, and lactate increased with MOSF and nutritional indices decreased, but only sepsis and IL-10 among the stress mediators were independently associated with the development of MOSF." (PMID 20490277, 2010). "High plasma IL-6, IL-8, and IL-10 levels have recently been associated with increased mortality in human sepsis-related ARF." (PMID 20546598, 2010). "With respect to the combination effect, our results show that the patients with 2 ATA haplotypes have higher sepsis morbidity rates, but this lacks statistical significance, although it is significantly associated with lower IL-10 production." (PMID 19939284, 2009). "A sustained high level of IL-10 in patients with sepsis has been associated with poor outcomes, presumably due to excessive anti-inflammatory effects." (PMID 19442306, 2009). "Demographic data and genotype frequencies of TNF and IL-10 polymorphisms in patients with sepsis and controls." (PMID 16859504, 2006). "(ii) The interesting conclusion is that SNP IL10-1082G/A increases predisposition to sepsis." (PMID 41598258, 2026). "Among these, the polymorphism rs1800896 (-1082 A/G), where there is the substitution of an Adenine with a Guanine, is repeatedly associated with the development of sepsis and its mortality due to its presence related to IL-10 mRNA expression, leading to an increased concentration of IL10." (PMID 41013722, 2025). "A previous study suggested that specific polymorphisms,such as the single nucleotide ploymorphism (SNP) A/G–1082 variant in the IL-10 promoter region, may belinked to an increased susceptibility to severe sepsis." (PMID 40026520, 2025). "Elevated IL-10 levels have been associated with clinical deterioration in patients with sepsis." (PMID 41517447, 2025). "Notably, carriers of the TLR4 rs4986790 mutation exhibited increased risk of severe infections and prolonged hospital stays, while IL-10 rs1800896 was linked to higher complication rates, particularly respiratory failure and sepsis." (PMID 40692949, 2025). "Different studies have been conducted on genes coding for inflammatory cytokines whose could predispose to the development of sepsis [e.g., IL-10 PD1 and WT1]." (PMID 41013722, 2025).